BRCA2 (BRCA2 DNA repair associated)
Diseases named in the same sentence as BRCA2 in open-access papers (continued):
Sharing a sentence is not in itself a finding about the gene and the disease.
prostate carcinoma (continued). "We assessed the incidences and characteristics of BRCA2 mutated cancers by targeted sequencing in 126 sets of advanced prostate cancer tissue sequencing data." (PMID 36362213, 2022). "The prevalence of BRCA1 and BRCA2 pathogenic variants was 0.38% and 4.30%, respectively, in prostate cancer patients." (PMID 36439508, 2022). "Germline BRCA1 and BRCA2 pathogenic variant carriers are recognized to be at increased risk for multiple cancers including breast, ovarian, pancreatic, and prostate cancer, with risk management recommendations for these cancers included in BRCA1/2 guidelines." (PMID 36497436, 2022). "BRCA1/BRCA2/ATM mutations were the first reported molecular alterations conferring sensitivity to PARP inhibitors in prostate cancer and are the most widely studied germline and somatic mutations in this setting." (PMID 35448200, 2022). "In prostate cancer, germline BRCA2 mutations have been associated with a more aggressive phenotype and poorer outcomes." (PMID 35740616, 2022). "The contribution of these genes (mostly BRCA2) to pancreatic cancer, male breast cancer, and prostate cancer susceptibility was also subsequently demonstrated." (PMID 36230512, 2022). "BRCA2 was one of the first genes implicated in hereditary prostate cancer and is responsible for a significant proportion of hereditary prostate cancer cases around the world." (PMID 35732815, 2022). "BRCA1-mutated prostate cancer has been shown to be less responsive to poly (ADP-ribose) polymerase (PARP) inhibitors as compared to BRCA2-mutated prostate cancer." (PMID 36185208, 2022). "The increasingly wide use of PARP inhibitors in breast, ovarian, pancreatic, and prostate cancers harbouring a pathogenic variant in BRCA1 or BRCA2 has highlighted the problem of resistance to therapy." (PMID 35681784, 2022). "PARP inhibitors are approved in breast, ovarian, pancreatic, and prostate cancers harbouring a pathogenic variant in BRCA1 or BRCA2, where PARP1 inhibition results mainly in synthetic lethality in cells with impaired homologous recombination." (PMID 35681784, 2022). "In the TCGA-localized prostate cancers, BRCA2 genetic alterations (mutations or deep deletion, somatic/germline) were found in 7 (4%) patients." (PMID 36362213, 2022). "Mutations in the BRCA2 gene, are associated with a significant, although more precisely undefined, risk of: ovary, prostate cancer and cancers of the gastrointestinal tract: stomach, colon, pancreas." (PMID 35395863, 2022). "Among prostate cancer patients carrying germline mutations, BRCA2 is the most common mutated gene among DNA damage repair pathway genes." (PMID 36439508, 2022). "The prostate cancer risk associated with BRCA2 PVs was 26.9% (95% CI, 20.5 to 34.7) by age 80 years and 33.1% (95% CI, 25.5 to 42.2) by age 85 years." (PMID 35077220, 2022). "ATM mutations and high-risk prostate cancer have been associated in some studies through screening of patients with advanced disease, although BRCA2 remains the only gene in which pathogenic variants have been consistently linked to aggressive prostate cancer." (PMID 35892882, 2022). "Germline mutations in BRCA1 and BRCA2 have been associated with an increased incidence of prostate cancer." (PMID 36551924, 2022). "Carriers of germline BRCA2 pathogenic sequence variants have elevated aggressive prostate cancer risk and are candidates for precision oncology treatments." (PMID 35715489, 2022). "Using the cBioPortal, we validated the co-occurrence or mutual exclusivity of gene mutations with BRCA2 genetic alterations in prostate cancer public datasets (6875 patients or 7151 samples from 22 studies)." (PMID 36362213, 2022). "Male BRCA1 and BRCA2 carriers are likely to benefit from more personalized breast and prostate cancer risk estimates." (PMID 34320204, 2022). "In general, inherited mutations in DNA repair genes, such as BRCA2, are associated with increased risks of lethal prostate cancer." (PMID 36429046, 2022).
prostate carcinoma (continued). "Mutations of BRCA1 and BRCA2 were well known as a risk factor for hereditary breast cancer and there were significantly increased risks of melanoma and prostate cancer in BRCA mutation carriers." (PMID 35932099, 2022). "The frequency of BRCA2 mutations was 4.5% in a large series of men with prostate cancer referred for testing with varying family histories, ethnicities and stages of disease." (PMID 35732815, 2022). "Male carriers of BRCA2 germline pathogenic sequence variants (PSV) experience 2.6-fold higher lifetime risk of prostate cancer and a 7.3–8.6-fold higher risk of developing early-onset (<65 years) prostate cancer." (PMID 35715489, 2022). "A preliminary analysis demonstrated that men who carry a BRCA2 mutation have a higher incidence of prostate cancer, a younger age at diagnosis and more clinically significant tumours than noncarrier controls." (PMID 35732815, 2022). "Patients with germline BRCA2 mutations have a risk as high as 20-fold of death due to prostate cancer compared to wild-type BRCA2 population." (PMID 34638258, 2021). "Olaparib is inhibiting PARP1, PARP2, and PARP3 and is used as a therapy for cancer in people with hereditary BRCA1 or BRCA2 mutations, which include some ovarian, breast and prostate cancers." (PMID 33481867, 2021). "Rare high-penetrance pathogenic variants can also contribute to the risk of aggressive prostate cancer, including those in known susceptibility genes such as BRCA2." (PMID 34830967, 2021). "BRCA2-related prostate cancer has been associated with a higher histologic grade and results in a poorer overall survival." (PMID 34356066, 2021). "On the other hand, 10 of 23 (44%) mutations in the BRCA2 gene fell in the prostate cancer cluster region (PCCR) at the 3′ terminal of the 7914 codon." (PMID 33710808, 2021). "Rahul was also found to have the cancer-predisposing BRCA2 variant and is concerned about developing prostate cancer." (PMID 34649841, 2021). "The other prostate cancer patient with BRCA2 P/LP variants had Gleason score 9, with another primary cancer including male breast cancer and squamous cell carcinoma of esophagus." (PMID 33649982, 2021). "These alterations, particularly mutations in BRCA2, are known to be associated with an increased risk of developing prostate cancer and more aggressive forms of the disease." (PMID 33106584, 2021). "Among the DDR genes, the most frequent germline mutation in mCRPC is BRCA2, as evidenced in a multicenter study conducted by the Stand Up to Cancer–Prostate Cancer Foundation (SU2C–PCF) consortium." (PMID 34948314, 2021). "This is because after three years of PSA screening, men with cancer-predisposing BRCA2 variants proved to have a higher incidence of prostate cancer, were younger at diagnosis, and were more likely to have clinically significant tumours." (PMID 34649841, 2021). "BRCA2 mutation carriers have a 5-year prostate cancer-specific survival (CSS) rate of ~50%, progressing rapidly from localized PC to mCRPC." (PMID 33478015, 2021). "Ten of 23 (44%) mutations in the BRCA2 gene fell in the prostate cancer cluster region (PCCR) at the 3′ terminal of the 7914 codon." (PMID 33710808, 2021). "It would be appropriate to include in this discussion that if prostate cancer does develop in a man with a cancer-predisposing BRCA2 variant, it is more likely to be clinically significant." (PMID 34649841, 2021). "Individuals who are BRCA2 mutation carriers have a 3-fold elevated risk for high-grade prostate cancer." (PMID 33947030, 2021). "Many BRCA1 and BRCA2 LGRs have been associated with hereditary breast, ovarian and prostate cancers." (PMID 34242281, 2021).
prostate carcinoma (continued). "In males, BRCA1 and BRCA2 PVs are responsible for the increased risk (higher in BRCA2 carriers) of developing breast and prostatic cancer." (PMID 34572941, 2021). "Germline BRCA2 mutations have consistently been associated with poor outcomes in prostate cancer at different disease stages, but the clinical impact of somatic BRCA2 alterations is unclear." (PMID 33106584, 2021). "On the other hand, the risk of developing male breast cancer, prostate cancer, pancreatic cancer, and melanoma in BRCA2 mutation carriers has been reported to be higher than in BRCA1." (PMID 34356066, 2021). "The younger diagnostic age of breast and prostate cancer in ALL families supported the suggested involvement of BRCA2." (PMID 34117277, 2021). "The risk of prostate cancer is also particularly increased in the male carriers of BRCA2 variants, with a lifetime risk of approximately 25–30%, and a tendency to a more aggressive phenotype." (PMID 34771713, 2021). "Germline mutations in BRCA1 and BRCA2 genes have been associated with a high risk of ovarian/breast and prostate cancers." (PMID 34242281, 2021). "Pancreas and prostate cancers were more common in families with pathogenic BRCA2 variant carrier probands." (PMID 33672545, 2021). "Patients carrying BRCA2 pathogenic mutations are more likely to progress to metastasis in prostate cancer." (PMID 34205170, 2021). "Germline BRCA2 mutation is associated with an aggressive prostate cancer phenotype and indicates higher risk for hereditary cancer." (PMID 34425813, 2021). "The first clinical trial of olaparib (NCT00516373) included three patients with advanced prostate cancer, including one patient with a BRCA2 mutation who had a greater than 50% reduction in PSA level and resolution of bone metastases." (PMID 33233320, 2020). "Consistently, the variant segregates with a prostate cancer case, sustaining the observation that BRCA2 variants are predominantly associated with increased risks of breast and prostate cancers and less with colon cancer." (PMID 33159495, 2020). "This is significant as a pathogenic variant in the BRCA2 mutation gene in particular which is linked to familial breast cancer also increases the risk of prostate cancer (Cancer Research UK 2018a, b)." (PMID 31965555, 2020). "Several hereditary mutations, most notably the BRCA2 gene, have been associated with an increased risk of prostate cancer." (PMID 32698438, 2020). "BRCA1 and BRCA2 mutations have been associated with prostate cancer (PCa) risk but a wide range of risk estimates have been reported that are based on retrospective studies." (PMID 31495749, 2020). "We recently reported prostate cancer (PCa) risk estimates for pathogenic variants (PVs) in BRCA2, based on a prospective cohort of male carriers." (PMID 32532514, 2020). "Prostate cancer screening in BRCA2 mutation carriers is recommended starting at the age of 40, whereas in BRCA1 mutation, carriers screening should be considered from the age of 40 onwards." (PMID 32655641, 2020). "Other studies have found that individuals with germline BRCA2 mutations are three-fold to 8.6-fold more likely to develop high risk prostate cancer." (PMID 32197306, 2020). "Another study showed a 33% response rate to olaparib in prostate cancer patients, where most of the responders had BRCA2 or ATM mutations." (PMID 32029455, 2020). "We found that men with mutations in one region of BRCA2 had a higher risk of prostate cancer than men with mutations elsewhere in the gene." (PMID 32532514, 2020). "Male BRCA2 mutation carriers have a high risk of developing prostate cancer, particularly high-grade disease." (PMID 31495749, 2020). "BRCA2 pathogenic variants located in a recently proposed prostate cancer cluster region confers higher risks of prostate cancer than other BRCA2 variants." (PMID 32532514, 2020).
prostate carcinoma (continued). "Nevertheless, BRCA2 has also been shown to increase the risk of prostate cancer by 8.6-fold in men over 65 (as well as pancreatic cancer) or a 2.64-fold increase among all men." (PMID 32698438, 2020). "Germline mutations in BRCA2 have been linked to a higher risk of prostate cancer (PCa), and high frequency of BRCA1 and BRCA2 (BRCA1/2) gene alterations was recently reported in metastatic castration-resistant PCa specimens." (PMID 30542053, 2019). "Results show an increased number of tumor-infiltrating lymphocytes, including potentially immunosuppressive FOXP3-positive lymphocytes, in BRCA2-mutated prostate cancers compared to the BRCA1/2 wild-type group, which harbored mostly extratumoral immune cells." (PMID 31549213, 2019). "Despite the compelling evidence indicating that BRCA2 mutations predispose carriers to an aggressive prostate cancer phenotype, the most appropriate screening strategy has yet to be elucidated." (PMID 30871108, 2019). "In a recent genome analysis, by comparing sequencing data obtained from castration-sensitive and castration-resistant prostate cancer, BRCA2 was the most frequently mutated, occurring in 12.7% of cases." (PMID 31242618, 2019). "Germline mutations and copy number changes in DNA damage repair (DDR) genes such as BRCA2 are associated with aggressive forms of prostate cancer (PCa)." (PMID 31631483, 2019). "BRCA1 mutation carriers increase the risk of prostate cancer in men aged < 65 years by 3.8-fold, and germline mutations in the BRCA2 gene increase prostate cancer risk by 8.6-fold." (PMID 31477094, 2019). "Future in vivo experiments in mouse models will assess the therapeutic potential of 6-TG in the treatment of BRCA2-deficient prostate cancers, and of 2-N-6-BP- and 2,6-DTP in the treatment of BRCA2-proficient, advanced prostate cancers." (PMID 31284411, 2019). "BRCA2 is the DDR gene most commonly mutated in advanced prostate cancer with up to 5.3% of these patients carrying a germline mutation." (PMID 30871108, 2019). "Taylor and coworkers have investigated prostate cancers occurring in men bearing germline BRCA2 mutations." (PMID 31366128, 2019). "Taken together, these findings suggest differences not only in the IT and ET distribution of immune cells in BRCA2-mutated and wild-type prostate cancers, but also in the composition of TIL populations." (PMID 31549213, 2019). "Of note, 5.3% of mCRPC patients harbored pathogenic germline BRCA2 mutations with a subsequent somatic event that resulted in biallelic loss, revealing a high frequency relative to primary prostate cancer." (PMID 31357527, 2019). "Eight BRCA2-mutated prostate cancer patients and eight BRCA1/2 wild-type patients matched for age, Gleason score, initial PSA, and initial TNM state were selected for this retrospective analysis." (PMID 31549213, 2019). "Poly ADP-ribose polymerase (PARP) inhibitors and platinum-based chemotherapy have proven to be effective in the treatment of other tumor types linked to BRCA1 and BRCA2 alterations and several trials are currently evaluating their efficacy in prostate cancer." (PMID 30871108, 2019). "Prostate cancer patients with inherited BRCA2 mutations have a very aggressive disease, with higher grade, advanced stage at diagnosis and poor survival, making a priority the development of novel therapeutic strategies for these patients." (PMID 31284411, 2019). "Germline mutations in BRCA2 have been linked to poor prognosis when patients are managed under the protocols currently approved for prostate cancer." (PMID 30871108, 2019). "BReast CAncer susceptibility gene 2 (BRCA2) is a tumor suppressor gene that when mutated confers increased sensitivity to several cancer types, including prostate carcinoma." (PMID 31284411, 2019). "It is likely that the correlations are due to the shared genetic factors such as penetrant mutations in BRCA2, which predisposes to breast, ovarian, lung, and prostate cancers." (PMID 32010612, 2019).
prostate carcinoma (continued). "BRCA2 expression is not only associated with the incidence of MC and ovarian cancer, but also affects the incidence of pancreatic cancer and prostate cancer." (PMID 31700821, 2019). "The pathogenic BRCA2 (c.3919G > T) mutation was detected in one family with a history of BC and prostatic cancer." (PMID 30982232, 2019). "Germline mutations in the BRCA2 tumor suppressor gene are associated with an increased lifetime risk of developing prostate cancer and increased risk of aggressive disease." (PMID 31366128, 2019). "The early diagnosis of BRCA2 mutations is important because these mutations have been associated with earlier onset and highly aggressive prostate cancers with poorer outcomes and with a higher sensitivity to PARP inhibitors and platinum-based chemotherapies." (PMID 31366128, 2019). "Inherited BRCA2 mutations that impair the gene function have been described in 3–5% of patients with advanced prostate cancer." (PMID 30871108, 2019). "In a further analysis, high rates of prostate cancer progression from localized to systemic disease were observed in a cohort of patients carrying germline mutations in the BRCA1/BRCA2 genes (n = 79)." (PMID 31242618, 2019). "IDCP has been associated with BRCA2 defects in familial prostate cancer, as it was shown that intraductal growth was significantly more prevalent in xenografts from BRCA2-mutated cases than in sporadic cases." (PMID 30825003, 2019). "Prostate cancer patients were included since a small proportion of them are associated with causative germline variants in BRCA1 or BRCA2." (PMID 30286154, 2018). "We also found a high frequency of melanoma, prostate cancer and male BC in BRCA2-mutated families, concordant with published literature." (PMID 29884136, 2018). "Especially in individuals with the BRCA2 mutation, prostate cancer is the most commonly diagnosed cancer, followed by MBC." (PMID 30577860, 2018). "More recently, a massive epidemiological study evaluated the association between this BRCA2 variant and the risk of breast, ovarian and prostate cancers." (PMID 29346284, 2018). "Deleterious mutations in BRCA2 was also implicated in a high risk of prostate cancer predisposition (8.6-fold in men ≤65 years) and more aggressiveness, as well as BRCA1 mutations although with a much lower frequency." (PMID 30333000, 2018). "Very high levels of GSTP1 methylation are also seen in prostate cancer, which is another male cancer that can be associated with BRCA2 mutation." (PMID 28893223, 2017). "This trial also showed a significantly higher rate of detecting intermediate to high-risk prostate cancer when BRCA2 men were screened." (PMID 28946846, 2017). "Collectively, our results underscore that a substantial proportion of primary metastatic or locally advanced prostate cancer patients who subsequently develop mCRPC harbor a deleterious BRCA2 mutation." (PMID 28676659, 2017). "A recent study undertaken in patients with castration-resistant prostate cancers harboring BRCA2 mutations demonstrated the polyclonal nature of resistant subclones." (PMID 29262651, 2017). "Men below the age of 65 carrying a germline mutation in BRCA1 or BRCA2 have a 3.4-fold and 8.6-fold, respectively, risk to develop prostate cancer, which make BRCA2 mutations the strongest known genetic risk factor for prostate cancer." (PMID 28676659, 2017). "The increased prevalence of prostate cancer in patients with germline BRCA1 and BRCA2 mutations has prompted consideration of prostate cancer screening in such patients by the IMPACT screening study." (PMID 28487881, 2017). "Germline mutations in the BRCA2 tumour suppressor are associated with both an increased lifetime risk of developing prostate cancer (PCa) and increased risk of aggressive disease." (PMID 28067867, 2017). "Given the current lack of these trials, we believe that it would be premature to omit taxanes from the therapeutic armamentarium to treat BRCA2-mutated prostate cancer patients." (PMID 28676659, 2017).